NKX2-3 (NK2 homeobox 3)
Diseases named in the same sentence as NKX2-3 in open-access papers (continued):
Sharing a sentence is not in itself a finding about the gene and the disease.
metabolic syndrome (1 paper, 2020). A cluster of metabolic risk factors for CARDIOVASCULAR DISEASES and TYPE 2 DIABETES MELLITUS. "The two upstream regulators—RARA and NKX2-3—appear to play a key role in controlling gene expression in HFD-MSCs and are important for adipocyte metabolism and differentiation; their dysregulation can contribute to metabolic syndrome and inflammation." (PMID 33361524, 2020).
oral squamous cell carcinoma (1 paper, 2021). "We detected FADD and NKX2-3 expression in oral squamous cell carcinoma cell lines HSC-3, HSC-4, and HSC-6 and human oral squamous cell line HOK by RT-qPCR." (PMID 34423028, 2021).
ovarian tumor (1 paper, 2008). "To validate the CGI microarray results, we confirmed hypermethylation at a NKX2-3 CpG island in ovarian tumor samples relative to normal tissue using bisulfite sequencing." (PMID 18826610, 2008).
uterine infection (1 paper, 2022). "The top three upstream regulators predicted to be inhibited in the endometrium of pregnant cows after uterine infection include 1) MAPK1 (kinase); 2) NKX2-3 (transcription regulator); and 3) IL1RN (cytokine)." (PMID 35358206, 2022).
tumor (9 papers, 2016 to 2024). "Consistent with tumor suppression, effectors of tumorigenesis (Myc, Myb, NKX2-3, and TRIM24), metastasis (NFE2L2), oncogenic transformation (FOXM1), and cell cycle (E2F2 and E2F3) were also inhibited in the presence of PRKN." (PMID 39213189, 2024). "The NKX2-3 protein was found to be located in the nucleus of tumor cells and was classified as a promising biomarker to predict the response of cancer patients undergoing FOLFOX4 chemotherapy." (PMID 34220946, 2021). "Notably, we noticed a higher expression level of NKX2-3 in the non-tumor tissues than in tumors for all three cancers." (PMID 39345334, 2024). "In the study of gastrointestinal neuroendocrine carcinomas, people found that the expression of NKX2–3 in liver metastases was lower than that in primary tumor tissues, suggesting that NKX2–3 may be associated with the process of tumor metastasis." (PMID 33402116, 2021). "Significant differences could also be observed in the expression of NKX2-3 in age, grade, stage, and tumor size." (PMID 34423028, 2021). "We show that in a small fraction of tumours, NKX2-3 plays a role in activating BCR signalling, which may be through a direct effect on Lyn/Syk tyrosine kinases." (PMID 27297662, 2016). "The BCPRS-related genes (YY1, POU5F1, NKX2-3, NR2F1, HEY1, and IFNA13) showed high heterogeneity in different cells; thus, the genes can independently predict cellular composition to reflect the microenvironment of tumor tissues." (PMID 34457116, 2021). "Although genetic changes may affect the level of mRNA expression, the findings of this study showed no significant variation in tumor copy number and nucleotide mutations of the six IMAAG genes (HEY1, IFNA13, NKX2-3, NR2F1, POU5F1, and YY1)." (PMID 34457116, 2021).
cancer (6 papers, 2018 to 2024). A tumor composed of atypical neoplastic, often pleomorphic cells that invade other tissues. "In the meantime, NKX2–3 and miR205 are inter-related, autophagy-related miRNAs were also found to be upregulated or downregulated in many cancers, and several studies point out to their potential use as biomarkers." (PMID 33402116, 2021). "However, there are few studies on the function of miR-205 in autophagy and cancer, especially for miR-205 and NKX2–3." (PMID 33402116, 2021). "The relevance between the expression of NKX2–3 and PD-1 was analyzed by TIMER, which is a comprehensive resource for systematical analysis of immune infiltrates across diverse cancer types." (PMID 33402116, 2021). "Interestingly, we also show that seven major gene regulators (TP73, RICTOR, NUPR1, NKX2‐3, MYCN, IL10, and EPO) involved in inflammation, oxidative stress, DNA damage, and cancer processes were affected by MP radiation." (PMID 29786969, 2018).
genetic disorder (1 paper, 2020). "NKX2‐3 has hitherto not been linked to a genetic disorder but the gene is a strong candidate gene for intestinal varices as it is expressed in human intestinal microvascular cells where it regulates VEGFA and MADCAM‐1 signalling." (PMID 31498527, 2020).
infection (1 paper, 2016). The state of being infected such as from the introduction of a foreign agent such as serum, vaccine, antigenic substance or organism. "IL1RN, MAPK1, TRIM24 and NKX2-3 were inhibited during infection in both classes, with significantly more inhibition in the ΔNF class relative to the ΔEF class." (PMID 27506615, 2016).
NKX2-3 also shares sentences with these, for which no sentence is quoted: MALT lymphoma (2 papers); anemia (1); B-cell neoplasm (1); brain tumor (1); chronic lymphocytic leukaemia (1); depression (1); digestive system diseases (1); follicular lymphoma (1); hypothyroidism (1); lung carcinoma (1); lymphoid neoplasm (1); megakaryoblastic leukemia (1); metastasis (1); multiple myeloma (1); myelodysplastic syndrome (1); nasopharyngeal carcinoma (1); ovarian carcinoma (1); prostate tumor (1); respiratory disease (1); Retinopathy (1); rheumatoid arthritis (1); Splenomegaly (1); type 1 diabetes mellitus (1); viral infection (1); ZIKV infection (1).